CD4 (CD4 molecule)
Diseases named in the same sentence as CD4 in open-access papers (continued):
Sharing a sentence is not in itself a finding about the gene and the disease.
Sepsis (continued). "In the cultured alveolar epithelial A549 cell line and the lungs of a mouse model of CLP-induced sepsis, EVs derived from CD4+ T cells exerted toxic effects through DGKK and its stimulation on the DAG/PKC/NOX4 signaling pathways." (PMID 36959535, 2023). "As crucial cells in the host immune response during sepsis, T lymphocytes are mainly composed of CD4+T cells and CD8+T cells, called helper T lymphocytes and effector T lymphocytes, respectively." (PMID 36873287, 2023). "Our data showed that the cell counts of CD4 T cells were highest in sham group while lowest in sepsis group." (PMID 37113759, 2023). "mTOR activation is completely inhibited in CD4+ lymphocytes of patients with sepsis; however, AMPKα activation was only slightly affected, and in the case of mTOR blockade, stimulated T cells were unresponsive." (PMID 37434129, 2023). "To determine the role of mTOR in ERS-induced CD4+ T cell apoptosis, we constructed a sepsis model with T cell-specific mTOR and TSC1 gene knockout mice." (PMID 35915740, 2022). "Taken together, these results suggest that the mTOR pathway plays a critical role in regulation of CD4 + T-cell apoptosis during sepsis, partly through regulation of A-L fusion-related protein transcription." (PMID 35435531, 2022). "We further investigated potential pathways mediating A-L fusion dysfunction in CD4 + T cells during sepsis." (PMID 35435531, 2022). "The BM is a preferential site for memory T cells during homeostasis and contributes to the recovery of the antigen-experienced memory CD4+ T cell pool in the periphery in a long term after sepsis." (PMID 36148245, 2022). "More importantly, miR-451a is able to regulate the differentiation of CD4+ T cells into Th cells, while the relation between miR-451a and Th cells in patients with sepsis remains unexplored." (PMID 35992658, 2022). "The blood glucose level of patients with sepsis was negatively correlated with the levels of CD4+/CD8+." (PMID 35664433, 2022). "The function of DCs is severely disturbed during sepsis as they rapidly lose their capacity to secrete the immune-activating cytokine IL-12 in response to microbial stimuli and to induce antigen-specific CD4+ and CD8+ T-cell responses." (PMID 36148245, 2022). "Meanwhile, the proportion of splenic Cd4+Cd25+Foxp3+ Treg continually increased after the onset of sepsis, and proportion of circulating Treg attained the highest level at 72 h." (PMID 35832091, 2022). "The mammalian target of rapamycin (mTOR) pathway modulates CD4 + T cell survival during sepsis through mechanisms that are not fully understood." (PMID 35435531, 2022). "The percentage of blood T-lymphocyte and CD4+ T-cell populations was maintained in mice pretreated with Gln in the sepsis group, and the expression of the antiapoptotic Bcl-2 gene was more pronounced and increased in splenic CD4+ T cells." (PMID 36211442, 2022). "We focus on the effects of ROS on ERS and CD4+ T cell apoptosis in the mouse sepsis model by using NAC to block ROS." (PMID 35915740, 2022). "To prospectively determine the systemic immune status of T cells in patients with sepsis, we determined the metabolic activity, killing function, and apoptosis-related receptor expression in CD4+ and CD8+ T cells." (PMID 35898496, 2022). "CD19hiFcγRIIbhi B cells, CD19lowFcγRIIblow B cells, and CD4+ T cells were sorted from PBMCs of patients with sepsis and healthy donors." (PMID 35983056, 2022). "Sepsis patients showed a significant decrease in the total percentage of CD4+ T cells as compared to w/o sepsis patients and HCs (p = 0.000 and p = 0.01)." (PMID 35720398, 2022). "Compared with the samples with sepsis, the infiltration of activated memory CD4 T cells and naive B cells was higher in the samples with sepsis-induced ARDS, while that of CD8 T cells was relatively lower." (PMID 34898369, 2022).
Sepsis (continued). "A preclinical study shows that conditional knockout of TIM-3 in CD4+ T cells or systemic knockout of TIM-3 reduces immunosuppression-related mortality in a mouse model of sepsis." (PMID 36209190, 2022). "CD4+ T-cell was reduced during the acute phase of sepsis, and then gradually increased during recovery." (PMID 36304125, 2022). "We can conclude from these experiments that VISTA expression plays a pivotal role in promoting acute CD4+ Treg survival/stability and regulating the cytokine milieu in acute sepsis to confer a survival benefit." (PMID 35401514, 2022). "During postinjury sepsis, T-cell dysfunction decreases the proliferation of CD4+ T cells and induces a shift toward a Th2-type response with accompanying loss of the Th1-type response." (PMID 36209190, 2022). "In sepsis, TNFR2 has been shown to associate with CD4+ T-cell impairment and post-septic immunosuppression by activation of Tregs." (PMID 35203474, 2022). "Functional experiments showed that sepsis-induced mregDCs potently activated naive CD4+ T cells, while promoted CD4+ T cell conversion to regulatory T cells." (PMID 35832091, 2022). "Our data suggest that A-L fusion dysfunction is an important mechanism mediating CD4 + T cell apoptosis in sepsis." (PMID 35435531, 2022). "In our study, we found that Bax, caspase-3, and BIM expression levels decreased, whereas Bcl-2 expression increased, and the CD4+ T cell apoptosis rate decreased significantly in the lck-mTOR sepsis mice." (PMID 35915740, 2022). "Autophagy dysfunction contributes to CD4 + T cell apoptosis during sepsis leading to impairment of adaptive immunity." (PMID 35435531, 2022). "The observation that more CD4 + leukocytes infiltrated the hearts of male mice in sepsis is consistent with a direct role for T lymphocytes in mediating acute cardiac inflammation, including autoimmune myocarditis." (PMID 35723764, 2022). "As to studies on cell-bound BTLA expression, results are conflicting, ranging from higher to lower CD4+ BTLA expression in sepsis compared to healthy volunteers." (PMID 35312715, 2022). "Through the intervention of mTOR, the stress and damaged state of CD4+ T cells in sepsis were improved, CD4+ T cell apoptosis was reduced, and the prognosis of the host was improved." (PMID 35915740, 2022). "Based on the functional analyses, we found that sepsis-induced mregDCs were potent at driving the phenotypic shift of naïve CD4+ T cells towards Tregs and Th2, implicating a role for mregDCs in promoting immune suppression." (PMID 35832091, 2022). "A higher proportion of CD4 + cells infiltrated the left ventricle in male iRHOM2−/− mice 18 h after sepsis (31.9 ± 5.1% CD45 + cells), compared to 13.4 ± 3.4% in female iRHOM2−/− mice (p = 0.02)." (PMID 35723764, 2022). "Adaptive immune responses mediated by CD4 + T cells play important roles in defense against infection, but are affected during the early stages of sepsis." (PMID 35435531, 2022). "Following the occurrence of sepsis, CD4+ T lymphocytes reportedly have undergone a phenotypical shift from helper T cell (Th) 1 to Th2 subset that possesses a decreased secretion of IL-2 and IFN-γ and impaired proliferative capacity." (PMID 35619710, 2022). "Oami and colleges reported inhibition of autophagy processes of CD4 + T cells during sepsis, which were proposed to lead to exaggerated apoptosis and immunosuppression." (PMID 35435531, 2022). "Sepsis restrained the abilities of spleen DCs to promote CD4+ T cell proliferation, which was partially counteracted by hydrolysing mtDNA by using DNase I." (PMID 36106559, 2022). "As a result, compared to the sepsis samples, the sepsis ARDS samples showed a higher infiltration of activated memory CD4 T cells and naive B cells and a lower infiltration of CD8 T cells." (PMID 34898369, 2022). "In particular, T lymphocytes are affected by sepsis-induced apoptosis with a decreased number of both CD4+ and CD8+ T cells." (PMID 36045686, 2022).
Sepsis (continued). "In vitro co-cultured MDSCs with CD4 T cells suppressed the proliferation and enhanced apoptosis of CD4 T cells in DC with sepsis patients." (PMID 35720398, 2022). "A substantial decline in lymphocyte (specifically CD4+ T lymphocytes) counts is well characterized in sepsis." (PMID 35619710, 2022). "We have previously confirmed that mTOR is involved in the immunosuppression of sepsis and that the apoptosis of CD4+ T cells can be attenuated by mTOR intervention." (PMID 35915740, 2022). "To further confirm the existence of ERS in CD4+ T cells during sepsis, we observed the ultrastructure of splenic CD4+ T cells by transmission electron microscopy (TEM)." (PMID 35759162, 2022). "The proportion of CD27+ activated CD4+ T cells was higher than in sepsis, while the CD56+ cytotoxic CD8+ T cell frequency was reduced." (PMID 35216673, 2022). "By working to alleviate ROS-mediated, ERS-induced CD4+ T cell apoptosis, the mTOR pathway is vital for CD4+ T cell survival in sepsis mouse model." (PMID 35915740, 2022). "Treg is a good candidate owing to explaining the impairment of the CD4+ T-cell compartment observed during sepsis due to their highly suppressive function." (PMID 35694296, 2022). "Previous studies indicated a relationship between autophagy disorders and exaggerated CD4 + T cell apoptosis during sepsis." (PMID 35435531, 2022). "Compared with CC and CA genes, patients with AA genotype showed a more significant downward trend of CD3+ T cells and CD4+ T cells from diagnosis to sepsis." (PMID 36714653, 2022). "Losses of CD4 + T cells via apoptosis occurs following sepsis onset and plays an important role in progression of immune suppression, which is closely associated with poor outcomes." (PMID 35435531, 2022). "In summary, we conclude that the enhanced expression of MDSCs in DC with sepsis was found to be responsible for suppressing CD4+ T cell functionality as well as expanding the CD4+FOXP3+ Treg activity." (PMID 35720398, 2022). "For example, the increased production of immunosuppressive cytokines and the impaired CD4+ T cell proliferation were similarly detected in elderly sepsis patients and CLP mice." (PMID 35990662, 2022). "Our study observed an increase in MDSCs and Tregs in cirrhosis patients with sepsis, with a decrease in CD4 T cells." (PMID 35720398, 2022). "As the expression of mTOR, T-bet and IFN-γ, and PD-1 by CD4+T cell fluctuates with sepsis severity, and the four markers displayed significant predictive significance for prognosis, which is consistent with our previous reported results." (PMID 35898496, 2022). "It clearly concludes that suppression of the immunosuppressive activity of MDSCs will decrease the expansion of CD4+FOXP3+ cells in sepsis." (PMID 35720398, 2022). "To characterize autophagy levels of CD4 + T cells in a mouse sepsis model, we assessed the expression of the autophagy proteins LC3II/I and p62/SQSTM1 in CLP mice and control mice." (PMID 35435531, 2022). "Dysregulation of CD4 + T cell apoptosis contributes to immunosuppression, which is universally observed in sepsis." (PMID 35435531, 2022). "This study demonstrates that Nrp‐1 knockdown lessens the viability of CD4+CD25+ Tregs during sepsis depending upon its grade and time." (PMID 34758202, 2022). "Abnormally increased expression of metabolic and apoptotic receptors on CD4+ T cells and decreased expression of functional factors are associated with poor prognosis in ICU patients with sepsis." (PMID 35898496, 2022). "In sepsis mouse models pretreated with Gln, the activation of CD4+ T cells was in equilibrium, and the expression of the anti-apoptotic protein Bcl-2 was more pronounced." (PMID 36211442, 2022). "MDSCs have an immunosuppressive function by expanding FOXP3+ Tregs and inhibiting CD4+ T-cell proliferation in sepsis." (PMID 35720398, 2022).
Sepsis (continued). "Although our data were limited in terms of Th cell subsets, risk genotype AA showed a more significant downward trend in the proportion of CD3+ T cells and CD4+ T cells from diagnosis to sepsis." (PMID 36714653, 2022). "A growing body of evidence shows that CD4+CD25+Foxp3+Tregs play a positive role in alleviating sepsis-induced rapid onset inflammation and improving the outcome of ALI/ARDS through both TGF-β-dependent and independent pathways." (PMID 35281010, 2022). "Orchestrating the balance among CD4+ T cell subpopulations and preventing damage to the intestinal barrier are important strategies for managing sepsis." (PMID 36079813, 2022). "Another group showed thermal injury-plus-sepsis or sepsis alone in rats lead to a suppressed CD4+ T proliferation/IL-2 production and a substantial down-modulation of lymphocyte survival in mesenteric lymph nodes." (PMID 35251032, 2022). "The low level of CD3+CD4+CD69+T/CD3+CD8+CD69+T ratio in G- sepsis (versus G+ sepsis) was mainly due to the upregulated CD3+CD8+CD69+ T (%) (CD8+T cell activation) and in part a consequence of the relatively loss of CD4+T(%)(CD4+T suppression)." (PMID 36703970, 2022). "Compared with sepsis samples, sepsis ARDS samples showed a higher infiltration of activated memory CD4 T cells and naive B cells, but a relatively lower infiltration of CD8 T cells." (PMID 34898369, 2022). "This indicated a possibility of medical treatment in modulating CD4 + T cells apoptosis during sepsis through pharmacotherapy." (PMID 35435531, 2022). "The balance among the subpopulations of Th and Treg cells as well as cytokines derived from these CD4+ T cells play crucial roles in the persistence and progression of sepsis." (PMID 36079813, 2022). "In a sepsis mouse model, it has been shown that the transfer of in vitro stimulated CD4+ Tregs was protective." (PMID 36142962, 2022). "This study firstly proved that IL-9-producing CD4(+) T cells and IL-9 were also closely related to the barrier injury and mortality in sepsis." (PMID 33941281, 2021). "Based on the 7-day prognoses of the sepsis patients or their levels of PD-1 expression on the surface of CD4+ T cells in the blood, we divided the patients into two groups." (PMID 33868224, 2021). "During sepsis, the reduction of CD4+/CD8+ ratio is closely related to sepsis-induced immunosuppression." (PMID 33717146, 2021). "This notion is highly related to our previous findings, wherein we observed sepsis-induced immunoparalysis ablated the subsequent development of EAE through the numeric reduction in naive autoantigen-specific CD4 T cells." (PMID 34702761, 2021). "Based on the well-known hallmarks of T cell exhaustion, our data suggests that CD4+ T cells present an exhausted phenotype in recurrent sepsis." (PMID 33717146, 2021). "We are the first to report that recurrent sepsis exacerbates CD4+ T cell exhaustion and decreases antiviral immune responses." (PMID 33717146, 2021). "In summary, CD4+ T cells are generally pathogenic agents in AKI induced by IR, nephrotoxic drugs, and sepsis." (PMID 34616308, 2021). "There is evidence that CD4+ T helper cell responses are impaired during sepsis and persistent failure of T cell activation in sepsis is associated with attenuated IFN-γ-producing CD8+ cytotoxic T cells and Th17 cell responses." (PMID 34489958, 2021). "While antibodies have been shown to be of upmost importance regarding septicemia, the response to pneumococcal colonization in the nasopharynx seems to solely depend on IL‐17‐secreting CD4+ TH cells." (PMID 33592135, 2021). "TIGIT was also upregulated on total CD4+ T cells, Foxp3+ Treg, CD4+ Foxp3– Tconv, and NK cells after sepsis in CA mice." (PMID 34100383, 2021). "Several studies have examined CD4+ T cells in elderly mice and patients with sepsis, revealing significant changes in their number, differentiation, and function." (PMID 33532141, 2021).
Sepsis (continued). "Together, our data suggests that recurrent sepsis exacerbates CD4+ T cell exhaustion and decreases antiviral immune responses, contributing to the significant morbidity, increased late mortality, and increased health care burden." (PMID 33717146, 2021). "EA applied to ST36 can maintain the intestinal mucosal immune barrier by increasing the number of CD3+ T cells and the ratio of CD4+/CD8+ T cells in rats with sepsis induced by cecal ligation and puncture." (PMID 34745304, 2021). "In a mouse model of cecal ligation puncture-induced sepsis with T cell-specific deletion of a mouse-specific autophagy gene (Atg7 or Atg5), peripheral CD4+ and CD8+ T cells rapidly underwent apoptosis and the number of secondary lymphoid organs decreased." (PMID 34335278, 2021). "Both elderly mice and patients with sepsis display smaller CD4+ T cell populations as CD4+ T cells are more prone to undergo sepsis-induced apoptosis in elderly individuals, and cell proliferation is impaired." (PMID 33532141, 2021). "Progressive paralysis likely due disseminated oral polio vaccine; progressive weakness; nosocomial sepsis; reduced CD4 cells, with normal number of C8, C19 and CD16/CD56 cells." (PMID 34093558, 2021). "We additionally analyzed lymphocyte subsets and CD4+ CD25+ forkhead box protein (FoxP3)+ Tregs at admission for sepsis workup as compared to age-matched controls." (PMID 34512621, 2021). "The percentages of tissue IL-9-producing CD4(+) T cells in the control group were significantly lower than that in the sepsis group (0.22%±0.04% vs. 1.02%±0.07%, P < 0.001) or the sepsis+IL-9 group (0.22%±0.04% vs. 1.57%±0.10%, P < 0.001)." (PMID 33941281, 2021). "TNFSF10 (TRAIL) and S100A8/9, were found to be significantly upregulated in late sepsis CD4+ and CD8+ T- lymphocyte subsets, respectively." (PMID 34484194, 2021). "During sepsis, CD4+ T cells undergo the greatest volume of apoptosis, and this event strongly correlates with patient survival." (PMID 34356636, 2021). "Other Murine studies also found that the frequency of Tregs increases in the acute phase of sepsis, while the total number of CD4+ T cells concomitantly decreases." (PMID 33021569, 2021). "The previous results found that CD4+lymphocytes increased significantly in sepsis-induced secondary S. aureus pneumonia mice." (PMID 34054345, 2021). "The BTLA density on the surface of peripheral blood CD4+ T cells was upregulated in sepsis survivors compared to healthy controls." (PMID 34163466, 2021). "Data of all consecutive patients with a diagnosis of sepsis at discharge and an available peripherical blood lymphocyte subset (CD4, CD8, CD16/CD56 and CD19) analysis at hospital entry were retrospectively collected between January 2015 and August 2018." (PMID 34372784, 2021). "The specific mechanism by which IL-9-producing CD4(+) T cells are involved in the mucosal barrier injury of sepsis needs further research." (PMID 33941281, 2021). "Numerous studies have investigated the effects of sepsis on CD4+T cells, including changes in their number, phenotype, and function." (PMID 33532141, 2021). "In this review, we will focus on immunosuppression through Tregs, as they are the most potent immunosuppressive member of the T-cell family, show a relative increase in the T-cell population in sepsis and hempen, e.g., CD4 T-cell function." (PMID 33021569, 2021). "In PH mice, TIGIT was upregulated on total CD4+ T cells, Foxp3+ Treg, CD4+ Foxp3– T conventional cells (Tconvs), and NK cells on days 2 and 3 after sepsis compared with sham controls." (PMID 34100383, 2021). "We found that LPS upregulates IL-38 in CD4+CD25+ regulatory T cells in septic mice, causing the improvement of host immune function and prognosis in the context of sepsis." (PMID 34955683, 2021). "More importantly, clinical studies using CYT107 (recombinant IL-7) have shown reversal of the marked loss of CD4+ and CD8+ T cells following sepsis." (PMID 34356636, 2021).